AEBP1 (AE binding protein 1)
Diseases named in the same sentence as AEBP1 in open-access papers (continued):
Sharing a sentence is not in itself a finding about the gene and the disease.
gastric cancer (10 papers, 2018 to 2025). A primary or metastatic malignant neoplasm involving the stomach. "This study aimed to investigate the expression pattern, prognostic significance and biological function of AEBP1 in human gastric cancer and to explore the underlying mechanism." (PMID 30097586, 2018). "We then detected the AEBP1 mRNA and protein levels with clinical GC and paracancerous tissue samples collected by ourselves and verified its high expression in gastric cancer tissues." (PMID 40296906, 2025). "To further explore the effects of AEBP1 on gastric cancer cells, we established cell lines with stable knockdown of AEBP1 by shRNA or with the overexpression of AEBP1." (PMID 40296906, 2025). "AEBP1 also reportedly promotes colon and gastric cancer cell proliferation and metastasis by activating the NF-κB pathway." (PMID 37686580, 2023). "AEBP1 silencing suppresses proliferation, invasion, migration, and metastasis of gastric cancer cells via the NF-κB pathway." (PMID 36352396, 2022). "AEBP1 also promotes the epithelial-mesenchymal transition of gastric cancer cells by activating the NF-kB pathway; this, in turn, predicts poor patient outcomes." (PMID 34439758, 2021). "AEBP1 was also shown to promote EMT in gastric cancer and colorectal cancer via activation of NF-κB pathway." (PMID 32565808, 2020). "The expression of AEBP1 is significantly increased in human gastric cancer and correlates with poor patient outcome; AEBP1 can significantly facilitate the proliferation, migration, invasion, and epithelial-mesenchymal transition of gastric cancer cells." (PMID 33224311, 2020). "AEBP1 in gastric cancer can significantly promote the proliferation, migration, invasion, and epithelial-mesenchymal transition of gastric cancer cells." (PMID 33224311, 2020). "AEBP1 functions as an oncogene in gastric cancer through promoting cell proliferation, migration and invasion, metastasis and epithelial-mesenchymal transition." (PMID 30097586, 2018). "In summary, our study illustrates that AEBP1 expression is increased in gastric cancer tissues and cell lines, and elevated expression of AEBP1 predicts poor survival in patients with both early- and late-stage gastric cancer." (PMID 30097586, 2018). "In vivo, we utilized a mouse peritoneal metastasis model and found that the combination of AEBP1 stable knockdown and Wnt pathway inhibitor Quercetin had the most significant inhibitory effect on the peritoneal intestinal metastasis of gastric cancer cell HGC27." (PMID 40296906, 2025). "Furthermore, AEBP1 knockdown and Wnt signaling inhibitor Quercetin synergistically inhibited the invasion and migration of gastric cancer cells, thereby restricting the peritoneal metastasis of GC." (PMID 40296906, 2025). "Thus, we tested the effect of knocking down AEBP1 in combination with Quercetin, a Wnt pathway inhibitor, on gastric cancer cell invasion and migration." (PMID 40296906, 2025). "Given that the function of AEBP1 in gastric cancer is rendered largely unknown, a particular study focused on the potential mechanisms by which AEBP1 promotes progression of gastric cancer (GC) cells." (PMID 32565808, 2020). "In addition, AEBP1 silencing has been recently associated to reduced migration, metastasis, and epithelial–mesenchymal transition (EMT) of gastric cancer cells." (PMID 32444628, 2020). "In addition, studies targeting AEBP1 inhibitors may lead to new therapeutic strategies for gastric cancer patients, but more experiments are needed to validate this." (PMID 40296906, 2025). "To clarify the spatial localization of AEBP1 in gastric cancer cells, by immunofluorescence experiment and western-blot after nuclear and cytoplasmic separation, we found that in addition to the existence of AEBP1 in the cytoplasm, part of AEBP1 was localized in the nucleus." (PMID 40296906, 2025). "Thus, AEBP1 might be a valuable prognostic marker of patients with gastric cancer and a potential target for treatment." (PMID 30097586, 2018).
gastric cancer (continued). "However, the role of AEBP1 in gastric cancer (GC) remains largely unknown." (PMID 30097586, 2018). "Several studies have focused on the prognostic values of CAF-related genes in other cancers, a 4-CAF-gene (COL8A1, SPOCK1, AEBP1 and TIMP2) prognostic signature was developed to predict the clinical outcomes and the response to anti-tumor therapies in gastric cancer." (PMID 35873482, 2022). "Furthermore, we detected the expression of AEBP1 in four GC cell lines (BGC823, MGC803, SGC7901, MKN-45) and a primary gastric cancer cell XN0422 (established in our laboratory) as well as in the immortalized gastric epithelium cell line GES-1." (PMID 30097586, 2018).
colorectal cancer (8 papers, 2018 to 2025). A primary or metastatic malignant neoplasm that affects the colon or rectum. "We previously demonstrated that adipocyte enhancer-binding protein 1 gene (AEBP1) is highly expressed in the stromal compartment of colorectal cancer and promotes tumor angiogenesis." (PMID 41373631, 2025). "We previously reported that AEBP1 is highly expressed in endothelial and stroma cells in colorectal cancer (CRC) and that upregulated expression of AEBP1 in endothelial cells facilitates tumor angiogenesis." (PMID 37686580, 2023). "This position is proximal to a binding site for miR-214 (3842–3848 bp), which was found to directly target and downregulate AEBP1 expression in colorectal cancer (HT-29) cells." (PMID 31299062, 2019). "Up-regulation of AEBP1 contributes to tumor angiogenesis in colorectal cancer." (PMID 36352396, 2022). "In addition, AEBP1 is upregulated in vascular endothelial cells and promotes tumor angiogenesis in colorectal cancer by inducing angiogenesis-related genes like AQP1." (PMID 34692770, 2021). "In colorectal cancer cells, AEBP1 expression is negatively regulated by miR-214." (PMID 31299062, 2019). "What is noteworthy is that, NCBI GEO gene expression database of TECs in colorectal cancer and lymphoma also verified the specific high expression of 7 out of these 12 ECM associated genes in TECs from colorectal cancer and lymphoma, i.e. SPON2, BMP-1, FN1, POSTN, THBS2, VCAN and AEBP1." (PMID 29541388, 2018). "The role that AEBP1 plays in augmenting the expression of EMT-related proteins via NF-κB pathway in bladder, gastric, and colorectal cancers was previously underscored." (PMID 32565808, 2020).
liver fibrosis (8 papers, 2019 to 2025). "Other studies have implicated the AEBP1 gene and the ACLP protein in fibrosis, including lung fibrosis, liver fibrosis and nonalcoholic steatohepatitis, and renal fibrosis." (PMID 39050735, 2024). "We identified 61 liver fibrosis-associated genes (e.g., AEBP1, PRRX1 and LARP6) that may serve as a repertoire of translatable drug target candidates." (PMID 34588551, 2021). "The current findings add to our understanding of the role of AEBP1 in hepatic fibrosis within the context of NASH in several ways." (PMID 31299062, 2019). "Furthermore, some studies have confirmed that the increased expression of AEBP1 correlates with the severity of liver fibrosis in patients with MASH." (PMID 40406118, 2025). "Furthermore, AEBP1 gene expression levels were increased in severe liver fibrosis compared to normal liver." (PMID 39930483, 2025). "Here we sought to investigate the relationship between AEBP1 and hepatic fibrosis." (PMID 31299062, 2019). "Here we sought to further investigate the relationship between AEBP1 and hepatic fibrosis in NASH." (PMID 31299062, 2019). "First, AEBP1-mediated regulation of fibrosis-specific genes, as well as those involved in ECM production and maintenance, suggest that this protein contributes to hepatic fibrosis through modulation of a gene network that may be specific to HSCs." (PMID 31299062, 2019).
bladder cancer (6 papers, 2017 to 2025). "AEBP1 was correlated with poor prognosis of bladder cancer due to its high expression and association with high degree tumor staging." (PMID 32565808, 2020). "Weighted gene coexpression network analysis- (WGCNA-) based studies demonstrated a strong association between AEBP1 expression and tumor progression in bladder cancer." (PMID 32565808, 2020). "Importantly, AEBP1 may be used as a diagnostic biomarker for tumor progression in bladder cancer and may be a potential target for individualized therapies for patients with high risk of MIBC." (PMID 32565808, 2020). "Here, we show that adipocyte enhancer binding protein 1 (AEBP1) attenuates the dependency of bladder cancer cell survival on the FACT complex via the expression of GLI1, a pivotal transcription factor in Hedgehog signaling." (PMID 40612002, 2025). "In AEBP1-high expressing bladder cancer cell lines, AEBP1 knockdown inhibited cellular proliferation and induced the marker expression of apoptosis and DNA damage/replication stress." (PMID 40612002, 2025). "By running a WGCNA analysis on the gene chip GSE31685 of bladder cancer, several hub genes were identified as potential biomarkers for bladder cancer, including AEBP1." (PMID 32565808, 2020). "A gene analysis study, using the GSE13507 dataset, highlighted AEBP1 as a potential prognostic biomarker in patients with bladder cancer (BC)." (PMID 32565808, 2020). "High expression of AEBP1 is related to bladder cancer stage and tumor patients’ prognosis." (PMID 36352396, 2022). "Nevertheless, as a potential prognostic biomarker, AEBP1 may serve as a therapeutic target in inhibiting the progression of bladder cancer." (PMID 32565808, 2020). "Studies that focused on the tumorigenic effects of AEBP1 in bladder cancer are scarce." (PMID 32565808, 2020). "Hence, a plausible mechanism by which AEBP1 promotes the development of bladder cancer is through the upregulation of tumorigenic processes via NF-κB pathway." (PMID 32565808, 2020). "Furthermore, gene ontology analysis revealed the biological function of AEBP1 in bladder cancer." (PMID 32565808, 2020).
fibrosis (5 papers, 2019 to 2024). the formation of excess fibrous connective tissue in an organ or tissue in a reparative or reactive process. "Among them, AEBP1 has been demonstrated to be associated with fibrosis in DCM and THBS4 has also been demonstrated to promote skin fibrosis." (PMID 38185631, 2024). "We also observed a significant trend of increasing AEBP1 expression concomitant with worsening severity of fibrosis with the highest hepatic levels found in patients with advanced fibrosis." (PMID 31299062, 2019). "Both miR-372-3p and miR-373-3p were significantly downregulated in NAFLD patients with fibrosis compared to those with normal histology, which would be consistent with upregulated AEBP1 expression." (PMID 31299062, 2019). "We observed a significant trend of increasing AEBP1 levels with increasing severity of fibrosis with advanced fibrosis (i.e., cirrhosis) > incomplete cirrhosis > bridging fibrosis (beta = 0.906; P = 0.028)." (PMID 31299062, 2019). "Aebp1 has a good performance in separating mild and advanced fibrosis patients." (PMID 37051599, 2023).
diabetes (4 papers, 2009 to 2025). "To extend AEBP1 expression findings from human liver biopsy tissue, we used in vitro models of diabetes and NAFLD by assaying the effects of glucose, fructose, and palmitate treatments on human stellate and liver cells." (PMID 31299062, 2019). "Second, the difficulties that were faced in the recruitment of diabetes patients in our department could result in an inability to determine the AEBP1 level in these patients." (PMID 34332599, 2021).
heart failure (4 papers, 2022 to 2024). Inability of the heart to pump blood at an adequate rate to meet tissue metabolic requirements. "In oxygen–glucose deprivation/reoxygenation (OGD/R)-exposed cells, adipocyte enhancer-binding protein 1 (AEBP1), which has been shown to be involved in cardiac fibrosis in heart failure, is upregulated." (PMID 39769255, 2024). "In human cardiac specimens of heart failure, transcription factor AEBP1 was abundantly expressed in activated fibroblasts and myofibroblasts, which co-expressed with fibrotic genes and ECM genes, indicating that AEBP1 may be a regulator of fibrosis in heart failure." (PMID 35454155, 2022).
oral cancer (4 papers, 2022 to 2025). "This research suggested that silencing of AEBP1 predisposes cisplatin-resistant oral cancer cells to ferroptosis via the JNK/p38 /ERK pathway." (PMID 36352396, 2022). "In addition, silencing adipocyte enhancer-binding protein 1 (AEBP1) predisposed cisplatin-resistant oral cancer cells to ferroptosis inducers in vitro, and ascorbic acid can induce ferroptosis in a model of oropharyngeal carcinoma." (PMID 40143107, 2025). "The results indicated that AEBP1 silencing suppressed the proliferation, migration, and invasion of oral cancer cells, thereby contributing to suppressing the progress of oral cancer cells." (PMID 36352396, 2022). "In this research, we demonstrated the role of AEBP1 silencing in promoting ferroptosis via the JNK/P38/ERK pathway in cisplatin-resistant oral cancer cells." (PMID 36352396, 2022). "The results demonstrated that silencing of AEBP1 can make oral cancer cells sensitive to SSZ-induced ferroptosis in vitro." (PMID 36352396, 2022). "AEBP1 silencing inhibited oral cancer cell proliferation, migration, and invasion after SSZ treatment." (PMID 36352396, 2022). "Thus, we explored the effect of AEBP1 silencing in regulation of ferroptosis in cisplatin-resistant oral cancer cells." (PMID 36352396, 2022). "However, the expression of AEBP1 and the role of AEBP1 silencing on ferroptosis in oral cancer are unclear." (PMID 36352396, 2022). "Taken together, these results indicated that AEBP1 might exert oncogenic effects in oral cancer progression, and AEBP1 silencing may suppress the progress of oral cancer by inhibiting proliferation, migration, and invasion." (PMID 36352396, 2022). "Taken together, AEBP1 may exert effects by targeting the JNK/p38/ERK pathway in cisplatin-resistant oral cancer cells." (PMID 36352396, 2022). "AEBP1 was highly expressed in oral cancer cells and tissues." (PMID 36352396, 2022). "The findings suggested that AEBP1 could be effective in the treatment of cisplatin-resistant oral cancer." (PMID 36352396, 2022). "Based on previous research, we speculated that AEBP1 silencing contributes to inhibiting oral cancer progression." (PMID 36352396, 2022). "The data showed that inhibition of AEBP1 promotes ferroptosis of oral cancer cells." (PMID 36352396, 2022). "The effect of AEBP1 silencing on SSZ-induced ferroptosis was explored in oral cancer cells." (PMID 36352396, 2022). "In addition, AEBP1 was up-regulation in oral cancer tissues compared with normal tissues (P < 0.01)." (PMID 36352396, 2022). "Therefore, based on previous research, we speculated that AEBP1 interacts with the JNK/p38/ERK pathway in cisplatin-resistant oral cancer cells." (PMID 36352396, 2022). "The functions of AEBP1 silencing and sulfasalazine (SSZ) treatment were determined on oral cancer cell lines and tumor xenograft mouse models." (PMID 36352396, 2022). "In this study, we demonstrated that AEBP1 is a critical regulator of ferroptosis, and AEBP1 silencing promotes ferroptosis by the JNK / p38 / ERK pathway in cisplatin-resistant oral cancer." (PMID 36352396, 2022). "In addition, other recent studies have shown that miR-214 inhibits AEBP1 expression and increases the chemosensitivity in CRC cells, and that AEBP1 knockdown induces ferroptosis in cisplatin-resistant oral cancer cells." (PMID 37686580, 2023). "In conclusion, the present study suggested that AEBP1 may be a novel regulator of ferroptosis by JNK/p38/ERK pathway and is also a potential therapeutic target in cisplatin-resistant oral cancer." (PMID 36352396, 2022). "The results demonstrated that AEBP1 silencing may promote ferroptosis of CAR cells in vitro and in vivo, thereby suppressing the progression of cisplatin-resistant oral cancer." (PMID 36352396, 2022).
steatosis (4 papers, 2019 to 2023). Increased lipid within the cytoplasm of cells. "Another study confirmed that hepatic AEBP1 is directly associated with the degree of steatosis, lobular inflammation, and fibrosis in NASH patients." (PMID 32660130, 2020). "The expression of AEBP1 was significantly elevated in fibrotic human liver compared to that with lobular inflammation, steatosis, and healthy liver, and increased with worsening fibrosis in NASH patients." (PMID 34588551, 2021). "In support of this database analysis, AEBP1 expression increases in the setting of NASH compared to simple steatosis in the livers of ApoE+/− mice." (PMID 32660130, 2020). "We observed significant differences in hepatic AEBP1 expression between fibrosis and normal (Padj = 1.5E-05), steatosis (Padj <0.001), and inflammation (Padj <0.001)." (PMID 31299062, 2019). "We confirmed that hepatic AEBP1 expression is elevated in fibrosis compared to lobular inflammation, steatosis, and normal liver, and increases with worsening fibrosis in NASH patients." (PMID 31299062, 2019). "Two hub genes Aebp1 and Fdft1 may play important roles in fibrosis and steatosis." (PMID 37051599, 2023).
Alzheimer disease (3 papers, 2021 to 2025). A progressive, neurodegenerative disease characterized by loss of function and death of nerve cells in several areas of the brain leading to loss of cognitive function such as memory and language. "Further, AEBP1 is associated with Braak staging and the degree of amyloid deposition, suggesting it is a marker of disease progression in Alzheimer’s disease (AD)." (PMID 34720873, 2021). "Next, we confirmed that the expression of AEBP1 was elevated in the brains of Alzheimer’s disease (AD) mice." (PMID 41516171, 2025). "In addition, using an Alzheimer’s disease mouse model, we analyzed the effect of regulating AEBP1 expression on microglial function in the diseased brain environment." (PMID 41516171, 2025).
atherosclerosis (3 papers, 2010 to 2022). A disease characterized by the build-up of fatty material and calcium deposition in the arterial wall resulting in partial or complete occlusion of the arterial lumen. "The overexpression of adipocyte enhancer-binding protein 1 (Aebp1) promoted atherosclerosis in AEBP1-transgenic mice with hyperlipidemia and atherosclerotic lesions in their proximal aortas." (PMID 35069436, 2021). "Studies have shown that AEBP1 plays an important regulatory role in the pathogenesis of atherosclerosis and may be a potential marker for the prevention and treatment of atherosclerosis." (PMID 36523769, 2022). "In contrast, AEBP1TG mice with targeted overexpression of AEBP1 in adipose tissue and macrophages are expected to be more susceptible to LPS-induced septic shock and Gram-negative bacterial infection-induced atherosclerosis compared to their WT counterparts." (PMID 20396415, 2010). "Finally, we anticipate that AEBP1 may serve as a likely molecular target towards the development of novel therapeutic strategies for the prevention or treatment of various inflammatory disorders such as atherosclerosis and septic shock syndrome." (PMID 20396415, 2010).